TLR2 (toll like receptor 2)
Diseases named in the same sentence as TLR2 in open-access papers (continued):
Sharing a sentence is not in itself a finding about the gene and the disease.
tumor (continued). "This BRAFV600E-induced immune suppression involves re-activation of the developmental factor TBX3, which in turn up-regulates CXCR2 ligands in a TLR2-NFκB dependent manner, leading to MDSCs recruitment into the tumor microenvironment." (PMID 35332119, 2022). "In the tumor, EV-DAMPs have been shown to engage both plasma membrane-localized TLRs (e.g., TLR2 and TLR4) and endosomal TLRs (e.g. TLR3, 7, and 9) driving potent responses via the transcription factor, NFκB." (PMID 35320943, 2022). "Our previous work had reported that SEP activated NK cells to kill tumor cells via both TLR2 and TLR4 signaling pathways." (PMID 35370674, 2022). "Our study found low TLR2 mRNA expression in LUAD tumor tissues, while TLR2 protein was high expression." (PMID 36117156, 2022). "During the process of malignant transformation, the level of TLR expression tend to elevate in transformed cells (including tumor cells); meanwhile, the expression of TLR2, 4, 5, which is normally on cell membrane, increases in cytosol in a diffused manner." (PMID 36479129, 2022). "It has been shown that TLR2 and TLR4 activation increases tumor progression by tumor-associated macrophages perhaps due to higher expression of these innate cells." (PMID 36389785, 2022). "P. anaerobius interacts with TLR2 and TLR4 on the colonocytes, and modulates tumor-associated macrophages, granulocytic tumor-associated neutrophils, and myeloid-derived suppressor cells to promote CRC." (PMID 35625485, 2022). "Of these eight genes, four (GNAI3, PCDH7, PSEN1, TNFSF9) were highly expressed in tumor tissues and were associated with poor prognosis, while CD69, SLC11A2, and TLR2 were poorly expressed in tumor tissue and were associated with good prognosis." (PMID 36117156, 2022). "In TNBC, TLR2 signaling has been shown to exhibit both pro- and anti-tumorigenic effects by inhibiting tumor growth and promoting lung metastasis." (PMID 35805158, 2022). "Existing studies have linked the expression of TLR2, TLR4, and TLR9 on GBM cells to tumor proliferation, invasion, and migration." (PMID 36311702, 2022). "We showed that virus-derived IFNγ synergised with a TLR2/1 agonist to induce nitric oxide production in macrophages as a strong proinflammatory signal of anti-tumour macrophage programming leading to tumour inhibition." (PMID 35804458, 2022). "In a unique cohort of preinvasive and early-invasive human NSCLC samples, we show that TLR2 is highly expressed in tumor epithelium and correlates with improved survival and clinical regression." (PMID 36351380, 2022). "Corresponding with the reduction in SASP expression in our Tlr2-null GEMM lung tumors, we identified a significant reduction in total and tumor-specific myeloid cells in tumor-bearing lungs from KrasLSL-G12D/+;Tlr2−/− mice." (PMID 36351380, 2022). "To enhance the activity of synthetic carbohydrate antigens in boosting the anti-tumor responses, we selected Pam3CSK4, which is an effective TLR2 agonist that activates the innate immune system, as the pattern molecule to add to the carbohydrate antigens." (PMID 34158858, 2021). "TLR2 mRNA and TLR2+ cell percentage was down-regulated in GC derived peripheral and tumor-infiltrating CD8+ T cells." (PMID 34620075, 2021). "HSP72 exposed on tumor-derived exosomes binds to TLR2 on MDSCs and triggers STAT3 signalling, promoting IL6 expression and immunosuppressive activity." (PMID 33544155, 2021). "Nuclear expression of both TLR2, which is a receptor, e.g., for peptidoglycan and lipoarabinomannan, and TLR5, a receptor for flagellin, correlates with large tumor size, while higher cytoplasmic TLR2 expression is observed within smaller tumors." (PMID 34208339, 2021). "Herein, we investigate the effect of BCG tumor treatment in TLR2−/−, TLR4−/−, TLR7−/− and TLR9−/− mice." (PMID 34341449, 2021).
tumor (continued). "Consistent with i.t. rlipoE7m-MoGM therapy, tumor regression induced by s.c. administration of TLR2 agonists and GM-CSF-containing fusion proteins is antigen dependent." (PMID 34599024, 2021). "Versican (a matrix proteoglycan) is secreted by tumor cells and stimulates metastasis through TLR2 signaling in myeloid cells." (PMID 34032639, 2021). "Both treatments, the SFV/IFNg vector alone or in combination with TLR2/1 Pam3 ligand, revealed inhibition of tumor growth in the orthotopic model." (PMID 34835178, 2021). "Among them, Versican promotes tumor expansion via TLR2 and upregulation of MT1-MMP and MMP9 expression." (PMID 33766119, 2021). "Here, we demonstrate that antibody-mediated immunotherapy combined with TLR2 stimulation improves the cytotoxic function of NK cells and subsequently enhances the elimination of tumor cells in vitro." (PMID 34681717, 2021). "DCA was also found to increase levels of toll-like receptor 2 (TLR2) expression on hepatic stellate cells (HSCs), which in turn also increase TLR2 agonist lipoteichoic acid (LTA) in tumor promoting senescence-associated secretory phenotype (SASP)." (PMID 34360566, 2021). "Exposure of the tumor cell supernatants to (toll-like receptor) TLR-2 or TLR-4 (principal receptors of HMGB1) reporter cells, however, did not induce a positive signal in these cells." (PMID 34876407, 2021). "TLR2 activation promoted cytolytic activity of both peripheral (18.48 ± 4.86%, paired t test, P = 0.0002) and tumor-infiltrating CD8+ T cells (18.48 ± 3.73%, paired t test, P < 0.0001) from GC patients." (PMID 34620075, 2021). "In the available literature, several studies were found to assess the effect of TLR2 expression in other neoplasms." (PMID 34439871, 2021). "mRNA expression of TLR2 in tumor-infiltrating CD8+ T cells was remarkable decreased in comparison with that in peripheral CD8+ T cells from NCs (LSD-t test, P < 0.01) and from GC patients (LSD-t test, P < 0.05)." (PMID 34620075, 2021). "This increase in inflammatory responses provided a tumor-promoting environment by regulating Toll-like receptor 2 (TLR2)." (PMID 34207035, 2021). "On the other hand, RSL3 induced significant upregulation of TLR2 expression in tumor tissues, which was reversed by the inclusion of rosiglitazone." (PMID 33432112, 2021). "TLR2 activation by versican also reduces dendritic cell anti-tumour response through IL-10 and IL-6 signalling, leading to the mitigation of conventional dendritic cell responses required for further downstream T cell activation." (PMID 34527586, 2021). "On the one hand, TLR2 activation has been related to tumor growth; on the other hand, TLR2-agonists act antitumorigenic inducing apoptosis on PDAC cells." (PMID 34298645, 2021). "TLR2-stimulated BE and EAC cells respond to TLR2 agonists by secreting chemokines and tumour-secretory factors which have TLR2 signalling capability." (PMID 33922955, 2021). "Enhanced tumor cell killing by immune cells after treatment with cetuximab in combination with TLR2 stimulation in vitro is supported by the in vivo data." (PMID 34681717, 2021). "A novel inhibitor of TLR-2, ortho vanillin, inhibited MMP-9, MMP-14, IL-6, and iNOS expression and decreased TLR-2-mediated pro-tumor M2 phenotype of brain resident macrophages." (PMID 34439380, 2021). "We leveraged GM-CSF to mature and recruit DCs in the tumor and simultaneously activated TLR2 on these cells." (PMID 34599024, 2021). "The combination of a TLR2 agonist and GM-CSF has synergistic effects that inhibit tumor growth and modulate tumor-infiltrating APCs." (PMID 34599024, 2021). "In our study, the addition of GM-CSF considerably enhanced the TLR2 agonist-induced antitumor response by promoting the infiltration of antigen-specific cytotoxic T cells in the tumor and the amount of perforin and IFN-γ secreted." (PMID 34599024, 2021).
tumor (continued). "While high expression and activation on tumor-associated macrophages (TAM) is related to tumor growth in a PDAC mouse model, TLR2-agonists have been shown to be an effective adjuvant immune-therapy against PDAC." (PMID 34298645, 2021). "Our results revealed that TLR2 agonists and GM-CSF cooperated to activate and recruit DCs, which substantially induced a therapeutic antitumor response in an established TC-1 tumor model." (PMID 34599024, 2021). "We created BM chimeras to dissect the role of TLR2 and -4 in stromal versus hematopoietic compartments for tumor growth." (PMID 34032639, 2021). "Biglycan acts as a DAMP, and here we provided evidence demonstrating that stromal biglycan promotes TNF-α expression in tumor cells through binding to TLR2 or TLR4, and subsequent activation of NF-κB and ERK signaling pathways." (PMID 33966638, 2021). "Tumor-resident TLR2 also essential for the tumor-triggered elevation of major histocompatibility complex class I, which not only increased antigen presentation but also contributed to the proliferation and activation of CD8+ T cells." (PMID 34620075, 2021). "To generate recombinant proteins with built-in TLR2 agonists and GM-CSF dual-function activity, we constructed tumor antigens with an N-terminal lipidation signal and fused them to MoGM and a hexahistidine tag at the C-terminus." (PMID 34599024, 2021). "Our studies identified a mechanism by which Mmp2 modulates antitumor activity: ligation of TLR2/4 on APCs promotes tumor infiltration of myelosuppressive populations while reducing tumor infiltrating CD4+ and CD8+ T cells, NK cells, and CD103+ DCs." (PMID 34032639, 2021). "To assess the role of host Tlr2 and Tlr4 in Mmp2-OE and Mmp2-KO tumor kinetics, we compared tumor growth in the Tlr2–/–Tlr4–/– DKO mice." (PMID 34032639, 2021). "On the contrary, in the context of oral carcinoma P. gingivalis promotes tumor growth in a TLR2-dependent manner." (PMID 34298645, 2021). "Recently, we have demonstrated that TLR2 is expressed on cancer stem cells (CSCs), which are a small population of cells at the apex of tumor cell hierarchy." (PMID 33321934, 2020). "Comparing the effects of EV derived from melanoma cells in vitro and in vivo, they found that only EV isolated from in vitro cultured tumor cells exerted a TLR2-dependent effect on MDSC in their system." (PMID 32878277, 2020). "Krestin acts as a selective TLR2 agonist, and activates both innate and adaptive immune systems; the anti-tumor activity of krestin is dependent on cytotoxic T cells and natural killer cells, but not dependent on CD4+ T cells." (PMID 33113890, 2020). "Zymosan, being known as a TLR-2 agonist, has been shown to augment the cure rate of tumor after Photofrin-PDT, as well as the levels of C3 complement." (PMID 31991650, 2020). "In another Finnish cohort of 73 OTSCC patients, the higher expression of TLR-2 was correlated with deeper tumour invasion and grade (p = 0.026; p = 0.021, respectively)." (PMID 33008143, 2020). "The expression of functional TLR2 is found in epithelial cells, while TLR2 is also expressed in many tumor cells and tissues." (PMID 32256204, 2020). "The activation of the TLR2 downstream signaling pathway also induces the expression of metalloproteinases involved in extracellular matrix degradation to promote tumor expansion." (PMID 33155039, 2020). "The physiological consequences of TLR2 activation vary according to the precise receptor(s) and cell type involved, but the result is often cell activation to aid in direct pathogen or tumor cell killing and the recruitment of additional immune effector cells." (PMID 32696994, 2020). "Hartley and colleagues showed that versican produced by mouse tumor cells stimulated monocytes to produce TNFα in a TLR2-dependent manner which in turn upregulated the expression of PD-L1 by mouse monocyte/macrophages." (PMID 32265939, 2020).
tumor (continued). "The interaction occurring among VCAN and TLR2 represents an effective link between inflammation and tumor progression." (PMID 33155039, 2020). "None of these effects was observed in TLR2−/− mice, confirming that both pro- and anti-tumor effects are TLR2-dependent." (PMID 33321934, 2020). "The supernatants from dying Ad-TK + GCV-treated GL26 tumor cells indicated that TLR2-dependent NFκB activation was inhibited when tumor cells were treated with glycyrrhizin, an antagonist of HMGB1." (PMID 33299138, 2020). "In colorectal cancer, TLR2 promotes tumor cell proliferation, migration, and invasion by activating the PI3K/AKT signaling pathway." (PMID 32426275, 2020). "Overall, the studies reported in this section demonstrate that TLR2 promotes tumor progression through cancer cell-intrinsic mechanisms, independently from its role in inflammation." (PMID 33321934, 2020). "Agonists for, e.g. TLR3 have been shown to induce apoptosis of tumor cells, and recently, a TLR2 agonist that generates macrophages with strong anti-tumor potential has been discovered." (PMID 32244723, 2020). "P. anaerobius can also interact with toll-like receptor 2 (TLR2) and TLR4 on colon cells, and modulate myeloid-derived suppressor cells (MDSCs), granulocytic tumour-associated neutrophils and tumour-associated macrophages (TAMs), thus promoting CRC." (PMID 33213502, 2020). "Among 825 CRC tumor samples, interpreting the TLR2 immunostaining proved successful in 775 (93.9%) samples." (PMID 32424768, 2020). "Using an A8 peptide that competitively binds to the domain of membrane HSP70 on tumor-derived exosomes can block the combination of HSP70 with TLR2 and restore the anticancer immune response." (PMID 32983146, 2020). "TLR2 is crucial for the detection of danger signals released by cancer cells and for the activation of the innate as well as of the specific anti-tumor immune response." (PMID 33321934, 2020). "Mice immunized with tumor-associated antigens (TAAs) together with the synthetic lipoprotein FSL-1, a TLR2/6 ligand, showed a significant decrease of tumor growth due to the induction of T helper type 2 (Th2) cells." (PMID 33321934, 2020). "In the present study, we confirmed that hypoxic primary tumors cause tumor cells to secrete HMGB1 and further promote neutrophil polarization to the CD62Ldim phenotype via the TLR2 signaling pathway, thereby promoting the formation of tumor metastases." (PMID 32943604, 2020). "The mechanisms of antitumor action following TLR2 agonist therapy, primarily based on preclinical data, have included NK cell activity as important in limiting tumor growth." (PMID 32696994, 2020). "Top GO terms were Toll-like receptor 2 signaling pathway, positive regulation of gamma-delta T cell activation, cellular response to interferon-beta, regulation of response to tumor cell, and regulation of immune response to tumor cell." (PMID 32587640, 2020). "Enhanced invasiveness of human gastric cells and greater vascularization of gastric tissue after the activation of TLR2 enhance tumor growth by inducing the production of IL-8, PGE2, and COX-2." (PMID 32012718, 2020). "Flt3L mediates recruitment of dendritic cells (DC) followed by DC activation via Toll-like receptor 2 (TLR-2)-mediated signaling which is stimulated by HMGB1 released by dying tumor cells into the tumor microenvironment (TME)." (PMID 33400737, 2020). "The opposite emerged for TLR2 expression, which increased in carcinoma cells and stained at a weaker intensity in the lymph nodes than in the bulk and invasive front of the tumor." (PMID 32424768, 2020). "The results of the present study indicated that TLR2 mRNA expression was higher in BCa tissues than in normal tissues and associated with tumor size, HER2 status, tumor subtype, and TNM stage." (PMID 32426275, 2020). "The expression of TLR2 was detected by immunohistochemistry, and tumor proliferation was detected by Ki67 labeling." (PMID 32256204, 2020).
tumor (continued). "In previous studies, we noted that natural killer (NK) cells, along with T cells, were enriched following therapeutic delivery of TLR2 activators to tumor sites in mice." (PMID 32696994, 2020). "The bacterium is also associated with upregulation of several inflammatory cytokines through a postulated miRNA-mediated activation of TLR2/TLR4 and activation of the JAK/STAT and MAPK/ERK pathways linked to CRC tumor progression." (PMID 31367996, 2019). "Toll‐like receptor 2 (TLR2) expressed on antigen presenting cells evokes a series of critical cytokines, which favor the development of tumor‐specific cytotoxic T lymphocytes (CTLs)." (PMID 31131189, 2019). "Using microarray analysis, transgenic mice/cells, and tumor models, we identify acGM-1.8 as a new, specific, and safe TLR-2 agonist with the potential to regulate both innate and adaptive anti-cancer immune responses in vivo." (PMID 31118418, 2019). "HMGB1 treatment resulted in significant upregulation of stem cell markers (Oct4 and Nanog) and CD133+ cell proportion in fresh tumor tissues, which were abrogated by silencing TLR2, YAP, or HIF-1α." (PMID 31558702, 2019). "While intravenous Listeria monocytogenes vaccination inhibited tumor growth in mice, injection of bacteria directly into tumor mass promoted tumor growth possibly due to TLR2 activation on malignant cells." (PMID 31695691, 2019). "We further identified acGM-1.8 as a specific agonist of TLR2 and validated its efficacy in producing macrophages with anti-tumor potential in vitro and in vivo." (PMID 31118418, 2019). "HMGB1 treatment promoted tumor regrowth and increased TLR2-YAP-HIF-1α signaling activation compared with the parental control." (PMID 31558702, 2019). "The binding of a natural ligand, Hsp105, found on the surface membrane of tumor-derived exosomes to TLR2 and TLR4, stimulates the secretion of IL-6 and PGE1." (PMID 31555295, 2019). "In this study, we have revealed that TRAPs can educate CD4+ T cells to promote tumor growth and metastasis through an HSP90α–TLR2–IL-6–IL-10/IL-21 axis and the induction of IL-10+ Bregs." (PMID 31300052, 2019). "Similar to MIP, a synthetic lipoprotein with TLR2/TLR1 engaging property has also been shown to induce tumor regression in the mouse model." (PMID 31590685, 2019). "HMGB1 released from dying tumor cells stimulates TLR-2, 4 or 9 signaling in DCs leading to antitumor effects." (PMID 31293597, 2019). "Our results indicate that EGT improves the tumor immune environment formed in response to TLR2/6 ligand by modulating cellular signaling and functions in TAM." (PMID 31019508, 2019). "Tumor volume in MIP-treated TLR2−/− mice were comparable with those in PBS-treated wild-type animals." (PMID 31590685, 2019). "Immunosuppression by the TLR2 and TLR9 combination regimen on host immune and tumor cells for controlling metastatic behavior was associated with a nominal effect on initial subcutaneously embedded tumor growth." (PMID 31508424, 2019). "A high TLR2 and a high TLR4 expression associated with pT2–4 tumours (p = 0.043; p = 0.049), and a high TLR7 expression associated with pT3 tumours (p = 0.025)." (PMID 31467388, 2019). "In summary, we report the design of a new, safe, and specific TLR2 agonist that can generate macrophages with strong anti-tumor potential in mice." (PMID 31118418, 2019). "In mice in which the mast cells in the tumor microenvironment did not express TLR2, while other cells retained TLR2 expression, the ability of a TLR2 agonist to inhibit tumor growth was ablated." (PMID 31167464, 2019). "In the present study, we further examined the role of MyD88 and TLR2 in MIP-mediated tumor regression." (PMID 31590685, 2019). "Further studies have shown that TLR2 enhances the immune suppression by stimulating the MDSCs survival, thereby restraining the anti-tumor T-cell activity." (PMID 31750245, 2019).